ADH1B (alcohol dehydrogenase 1B (class I), beta polypeptide)
Description:
Catalyzes the NAD-dependent oxidation of all-trans-retinol and its derivatives such as all-trans-4-hydroxyretinol and may participate in retinoid metabolism. In vitro can also catalyze the NADH-dependent reduction of all-trans-retinal and its derivatives such as all-trans-4-oxoretinal. Catalyzes in the oxidative direction with higher efficiency. Has the same affinity for all-trans-4-hydroxyretinol and all-trans-4-oxoretinal.
Synonyms: ADH2; HEL-S-117
Tractability: Small molecule: an approved drug acts on it; a structure with a bound ligand is known; it has a high-quality binding pocket; it belongs to a druggable protein family. Antibody: its Gene Ontology location is reachable by antibodies, with high confidence. PROTAC: a small molecule that binds it is known.
Target class: Enzyme; Oxidoreductase
Safety:
Unwanted effects reported when the protein is acted on. In parentheses: how it was acted on, where the effect was seen, and who reports it.
alcoholism (source: ClinPGx)
Gene: Protein-coding gene on chromosome 4 (99,304,971 to 99,321,659, reverse strand). Ensembl gene ENSG00000196616.
Subcellular location: Cytoplasm
Subcellular location (Human Protein Atlas): Cytosol; Plasma membrane; Basal body; Nucleoplasm; Primary cilium; Primary cilium transition zone
Pathways (Reactome):
Metabolism: Ethanol oxidation
Gene Ontology:
Molecular function: alcohol dehydrogenase (NAD+) activity; all-trans-retinol dehydrogenase (NAD+) activity; protein binding; zinc ion binding; oxidoreductase activity
Biological process: retinoid metabolic process; retinoic acid metabolic process; retinol metabolic process
Cellular component: cytosol; cytoplasm
Genetic constraint (gnomAD): Loss-of-function variants: 24 observed, 33.33 expected, observed/expected ratio (o/e) 0.72, 90% interval 0.52 to 1.01. The upper end of that interval is the gene's LOEUF score, 1.01, which puts it in group 4 of 6, group 1 being the genes least tolerant of losing a copy. Missense variants: 400 observed, 446.8 expected, observed/expected ratio (o/e) 0.9, 90% interval 0.82 to 0.97. Synonymous variants: 159 observed, 163.43 expected, observed/expected ratio (o/e) 0.97, 90% interval 0.85 to 1.11.
Homologues: Orthologues: chimpanzee ADH1B (99% identical), macaque ADH1B (95% identical), pig ADH1C (85% identical), mouse Adh1 (83% identical), rat Adh1c (82% identical), zebrafish zgc:77938 (58% identical), zebrafish adh5l (57% identical), zebrafish adh8a (56% identical), zebrafish adh8b (52% identical), Caenorhabditis elegans D2063.1 (21% identical), Caenorhabditis elegans adh-1 (20% identical), Caenorhabditis elegans sodh-2 (19% identical), and 2 more. Paralogues in human: ADH1C (94% identical), ADH1A (94% identical), ADH7 (69% identical), ADH6 (63% identical), ADH5 (62% identical), ADH4 (61% identical), CRYZ (21% identical), SORD (21% identical), RTN4IP1 (21% identical), VAT1 (21% identical), TP53I3 (21% identical), MECR (20% identical), and 5 more.
Diseases named in the same sentence as ADH1B in open-access papers:
ADH1B is named in the same sentence as 139 diseases in open-access papers, as found by Europe PMC text mining. Sharing a sentence is not in itself a finding about the gene and the disease. The quoted sentences say what the papers report.
alcohol dependence (72 papers, 2005 to 2025). Physical and psychological dependence on alcohol. "For instance, genetic variations in the ADH1B gene, which encodes an alcohol dehydrogenase enzyme, have been linked to alcohol dependence." (PMID 40282331, 2025). "Conversely, among individuals with alcohol dependence, the ADH1B*2 allele is associated with an increased risk of liver cirrhosis, with an age-adjusted odds ratio for cirrhosis of 1.58 (95% confidence interval; 1.19–2.09)." (PMID 40943250, 2025). "In the present study, the ADH1B rs1229984 CC genotype was also found to be significantly associated with alcohol‐induced mental disorders (OR = 2.93, p = 0.002) and alcohol dependence syndrome (OR = 3.95, p < 0.001)." (PMID 35670037, 2023). "Among the currently known genes, ALDH2 and ADH1B had the greatest impact on the risk of alcoholism, which can result in accumulation of acetaldehyde that causes DNA damage and promotes ESCC development." (PMID 37795758, 2023). "One theoretical explanation for that result is collider bias, in which flushing and ADH1B each influence alcohol dependence independently, and amongst cases become associated." (PMID 37875790, 2023). "Some ADH variants, including the ADH1B*48His (rs1229984) mutation in the ADH1B gene, reduce the risk of alcoholism and are under positive selection in multiple human populations." (PMID 36026493, 2022). "People with low alcohol dehydrogenase 1B activity (ADH1B*1/*1 genotype) have a high risk of developing head and neck cancer and alcoholism." (PMID 36028843, 2022). "The p.His48Arg in ADH1B was associated with reduced risk of alcohol dependence (P = 2.6 × 10−64, OR = 0.31, ncases = 60,800)." (PMID 36280732, 2022). "Meta-analyses have suggested that the ADH1B*1 allele is associated with a three-fold increase in the risk of alcoholism relative to the ADH1B*2, which is considered as a protective function against alcohol abuse and alcoholism." (PMID 33924016, 2021). "The increased number of ALDH2*1 allele and ADH1B*1 allele in the ALDH2 and ADH1B genotype combinations resulted in the higher risk of alcohol dependence in women as well as men, and similar ORs of alcohol dependence was observed between women and men." (PMID 34310648, 2021). "In male Han Chinese, the ADH1B p.H48R variation was positively associated with alcohol dependency; however, the ALDH2 p.E504K variation was negatively associated with alcohol dependency." (PMID 34073884, 2021). "It is plausible that the association of SNP rs1229984 with both BMI and alcohol dependence represents independent effects of ADH1B in adipose and liver tissues." (PMID 33479282, 2021). "One variant in the ADH1B gene reported to be protective for alcohol dependence (rs1229984) shows a significantly higher allele frequency in Roma without a clear ancestry origin." (PMID 34220960, 2021). "A recent study from Japan found that those with slow metabolizing ADH1B enzyme increase susceptibility to hepatic steatosis in men with alcohol dependence." (PMID 32143280, 2020). "These symptoms altogether are considered to be a genetic deterrent to heavy drinking and alcoholism among East-Asians, where the predisposing alleles in rs1229984 of ADH1B is around 10% in contrast to the 90% found in the Hungarian and European populations." (PMID 31011876, 2019). "A previous study has established the functional effect of the SNP rs1229982 in the proximal promoter region of ADH1B that was associated with alcoholism." (PMID 29166882, 2017). "A variant of the ADH1C gene, the ADH1C*1 allele, also has been well studied with respect to alcohol dependence, but the results have been inconsistent because of limited sample sizes, ethnic variation, and the close proximity of the ADH1B and ADH1C genes." (PMID 27163368, 2016). "This meta-analysis also examined the effect of ALDH2*2 and ADH1B*2 alleles in combination on the risk for alcohol dependence." (PMID 27163368, 2016).
alcohol dependence (continued). "Significant associations for the ADH1B*3 allele and alcohol dependence primarily have been found in individuals of African ancestry where this genetic variant is most prevalent." (PMID 27163368, 2016). "ADH1 genes (including ADH1B) have been studied extensively on both a functional and a population-genetic level, as they are thought to be one of the major drivers of alcoholism risk." (PMID 26402243, 2015). "A proportion of individuals of African origin also have a variant in ADH1B (ADH1B*3) that has been demonstrated to be protective against alcohol dependence in African Americans and Afro-Caribbeans." (PMID 25527893, 2014). "Some examples of variability in response to alcohol based on differences in ADH genotype include variants in ADH1B (e.g., ADH1B*2) that confer protection against alcohol dependence in East Asians, as well as Europeans, though at a much lower frequency." (PMID 25527893, 2014). "In a second population of Mexican Americans, presence of at least one ADH1B*2 allele was found in 13% of the population, and was associated with protection against alcohol dependence." (PMID 25527893, 2014). "Previous studies have shown that interactions between SNPs across these genes are apparent in the risk of alcoholism, in particular between ADH1B and ADH7 and between ADH4 and ADH1A." (PMID 23166662, 2012). "An association study in Han Chinese indicates that the individuals carrying ADH1B*47His have the lowest risk for alcoholism." (PMID 20089146, 2010). "In previous case-control studies, it was found that the ADH1B*47His allele decreased the risk for alcoholism both in Asian and European populations." (PMID 18382665, 2008). "In the Asian populations included in the alcoholism correlation studies, both derived allele frequencies of ADH1B*47His and the promoter polymorphism are high." (PMID 18382665, 2008). "Some papers also doubted the significance of the association between ADH1B*47His and alcoholism in European populations as the frequency of the ADH1B*47His is also low." (PMID 18382665, 2008). "Among people of Jewish descent, the ADH1B*2 allele is found at moderate frequencies and reduces binge drinking and risk for alcoholism." (PMID 17718394, 2007). "The ADH1B*2 allele, which is associated with particularly rapid ethanol oxidation, has shown protective effects against alcohol dependence in a variety of populations." (PMID 17718394, 2007). "For example, among Chinese living in Taiwan, the odds ratio for developing alcoholism for a person carrying a single ADH1B*2 allele is 0.19, and for a person carrying two ADH1B*2 alleles, 0.12, compared with a person carrying two ADH1B*1 alleles." (PMID 17718394, 2007). "The ADH1B*3 allele had a significant protective effect on risk for alcoholism in a set of African-American families selected for having multiple alcoholic members." (PMID 17718394, 2007). "Non-coding SNPs in the ADH1A and ADH1B genes also appear to be associated with alcoholism risk in the European-American family sample." (PMID 17718394, 2007). "This conclusion is supported by other recent studies, which also found that the ADH1B*3 allele was significantly associated with a reduced risk for alcohol dependence among African Americans." (PMID 17718396, 2007). "In East Asians, in whom the ADH1B*2 allele is found at high frequency, it is protective against alcoholism." (PMID 17718394, 2007). "In Asians with no ALDH2*2 alleles, possession of one variant ADH1B*2 allele was associated with a four-fold reduction in alcohol dependence and possession of two ADH1B*2 alleles was associated with a five-fold reduction." (PMID 17718397, 2007). "First, the presence of ADH1C*1 in Indo-Trinidadians and ADH1B*3 in Afro-Trinidadians is associated with reduced risk for alcoholism." (PMID 17718398, 2007).
alcohol dependence (continued). "These analyses suggest that in this sample of Trinidadians, the ADH1B*3 allele has a protective effect against development of alcoholism; however, in people who do become alcohol dependent, the allele is associated with an enhanced risk for liver disease." (PMID 17718398, 2007). "Studies have demonstrated that a certain variant of the gene encoding ADH1B (ADH1B*3) is associated with a reduced risk of alcoholism in Afro-Trinidadians, as is a variant of the gene encoding ADH1C (i.e., ADH1C*1) in Indo-Trinidadians." (PMID 17718398, 2007). "Another analysis investigated the association of alleles of another type of ADH, ADH1B, with alcohol dependence, drinking history, and liver function in Indo- and Afro-Trinidadians." (PMID 17718398, 2007). "Previous ADH1B polymorphism studies have shown that the frequency of ADH1B*1 is significantly higher in men with type II alcoholism (primarily genetic, that starts during adolescence) than in men with type I alcoholism and in healthy men." (PMID 38886650, 2024). "Of the newly identified variants, rs1229984 in ADH1B associated with a lower risk of alcohol dependence, alcoholic liver disease (ALD), cardiovascular risk factors (for example, hypertension, body mass index (BMI)) and cardiovascular disease (for example, coronary artery disease)." (PMID 38632349, 2024). "ADH1B*1 is the less active form of ADH1B, that protects against a rapid increase of acetaldehyde in the blood, contributing to an increased susceptibility to alcoholism." (PMID 38886650, 2024). "Studies have shown that ALDH2 and ADH1B are associated with reduced rates of alcohol dependence." (PMID 37795758, 2023). "A distinct ADH1B gain-of-function Arg369Cys variant, rs2066702, found in African-American and some Native American populations was found to correlate with lower incidence of alcoholism, lower maximal habitual alcohol intake, and less problematic alcohol use." (PMID 37051560, 2023). "However, in a candidate gene study involving ALDH2 and ADH1B in a sample of Japanese individuals with alcohol dependence, ADH1B did associate with flushing." (PMID 37875790, 2023). "Combined evaluation of the alcohol flushing status and the ALDH2 plus ADH1B genotype may show superior ability than that of either alone for predicting the risk of alcohol dependence." (PMID 34310648, 2021). "The combination of the alcohol flushing status and ALDH2 plus ADH1B genotype may have a better performance for predicting the alcohol-dependence risk in comparison with alcohol flushing alone or genotyping alone." (PMID 34310648, 2021). "ADH1B has been widely studied and research shows that individuals with the rare allele consume less alcohol than those with the typical allele and have a reduced risk of alcoholism." (PMID 30648224, 2020). "The ancestral alleles at ADH1B rs3811801 and rs1229984 are nearly fixed in the Scythian dataset, as they are in modern Europeans (the derived alleles, which confer some resistance to alcoholism, are under selection in East Asians46, 47)." (PMID 28256537, 2017). "Thus, Asians who carry the ALDH2*2 allele show a greater protective effect (i.e., a lower risk of alcohol dependence) from the ADH1B*2 allele than do people who only carry the functional ALDH2*1 allele." (PMID 27163368, 2016). "Similarly, the ADH1B*3 allele has been associated with protection against alcohol dependence in Afro-Trinidadians." (PMID 17718395, 2007). "Indeed, indications for an association between ADH1B genotype and alcohol consumption, alcoholism or adverse reactions such as flushing were observed in previous studies." (PMID 15886702, 2005). "Additionally, the CC genotype of ADH1B rs1229984 is significantly associated with cancer of the larynx, pharynx, and nasal cavities (OR = 1.55, p = 0.001), alcohol‐induced mental disorders (OR = 2.93, p = 0.002), and alcohol dependence syndrome (OR = 3.95, p < 0.001)." (PMID 35670037, 2023).
alcohol dependence (continued). "One of the coding variant in ADH1B is rs1229984, which leads to the replacement of Arg48 with His48, is common in Asian populations and the enzymes with His48 oxidize ethanol approximately 70- to 80-fold faster than those with Arg48, eventually reduces their risk for alcoholism." (PMID 24485404, 2014). "The protective effect of the ADH1B*2 allele against alcoholism vanished in antisocial alcoholics, and the protective effect of the ALDH2*2 allele might disappear in individuals with antisocial personality disorder (ASPD) and carrying the MAOA-uVNTR 4-repeat allele." (PMID 22550993, 2012). "Considering that ADH1B rs1229984 is more common in the East Asian population than in Europeans, more studies are needed to investigate the role of ADH1B in the etiology of alcohol dependence among the East Asian population." (PMID 37795758, 2023). "Specific alleles of rs1229984 and rs671 in the ADH1B and ALDH2 genes, accordingly, lead to physical reactions like facial flushing and nausea after alcohol consumption, lowering the risk of alcohol dependence." (PMID 37628681, 2023). "Another major alcohol-metabolizing enzyme is alcohol dehydrogenase 1B (ADH1B), which is related to the risk for alcohol dependence in Caucasians." (PMID 34441974, 2021). "Knowing an individual’s own ALDH2 plus ADH1B genotype is a growing preventive strategy against alcohol dependence." (PMID 34310648, 2021). "Genome-wide association study (GWAS) results revealed that both ADH1B p.H48R and ALDH2 p.E504K variants are associated with alcohol dependency in Chinese people; however, only the ALDH2 p.E504K variant is associated with drinking behavior in Japanese people." (PMID 34073884, 2021). "Previous GWAS results revealed that both ADH1B and ALDH2 variants are associated with alcohol dependency in Chinese people; however, only the ALDH2 variant is associated with drinking behavior in Japanese people." (PMID 34073884, 2021). "The present study showed that the never or former flushing by the simple flushing questionnaire was a strong independent risk factor of alcohol dependence in any ALDH2 and ADH1B genotype combination carriers in both men and women." (PMID 34310648, 2021). "Functional variant alleles of ADH1B*2 and ALDH2*2 have been consistently replicated to show protection against developing alcoholism and confined in the Asian population, including Han Chinese, Japanese, and Koreans." (PMID 34439848, 2021). "Commercially available ALDH2 plus ADH1B genotyping has been used as a preventive tool against alcohol dependence in Japan." (PMID 34310648, 2021). "Several risk factors for DIULs, including genetic polymorphisms of alcohol and aldehyde dehydrogenases (ADH1B, rs1229984; ALDH2, rs671), have been demonstrated in Japanese alcohol-dependent men." (PMID 30629674, 2019). "The del− genotype was associated with alcoholism, especially in male population, and alcoholic patients with the del− continued to drink despite they had protective ALDH2*2 and ADH1B*2 alleles." (PMID 29234453, 2017). "In particular, the ADH1B*2, ADH1B*3, ADH1C*1, and ALDH2*2 alleles have shown protective associations with alcohol dependence." (PMID 27163368, 2016). "Certain genetic variants (i.e., alleles)—particularly the ADH1B*2, ADH1B*3, ADH1C*1, and ALDH2*2 alleles—have been associated with lower rates of alcohol dependence." (PMID 27163368, 2016). "The findings assessing this proposed mechanism of action—that ADH1B and ADH1C variations reduce alcohol dependence risk through elevated acetaldehyde levels, heightened responses to alcohol, and reduced drinking—have been inconsistent." (PMID 27163368, 2016). "Of the studies conducted, one study found that the ADH1B*1 and ADH1C*2 alleles were both associated with alcohol dependence in Mexican Americans." (PMID 25527893, 2014).